MCL1 (MCL1 apoptosis regulator, BCL2 family member)
Diseases named in the same sentence as MCL1 in open-access papers (continued):
Sharing a sentence is not in itself a finding about the gene and the disease.
multiple myeloma (continued). "The short half-life of MCL-1 also affects the potency of mitotic inhibitors in myeloma." (PMID 33308268, 2020). "MCL-1 in myeloma is regulated at both the transcriptional and the functional levels." (PMID 33308268, 2020). "Because the use of BCL2 and MCL1 inhibitor combination could also increase toxicities, we paid attention to evaluate suboptimal doses of each inhibitor in myeloma cells." (PMID 32371863, 2020). "The present study aimed to determine whether the combination of BCL2 and MCL1 inhibitors at low doses could be of benefit for myeloma cells beyond the single selective inhibition of BCL2 or MCL1." (PMID 32371863, 2020). "Consequently, MCL-1 also appears as an attractive drug target to overcome the immunosuppressive features within the myeloma niche." (PMID 33308268, 2020). "It is yet to be determined whether MCL-1 antagonism is effective in clinical trials of BLBCs, but there are currently two Phase I clinical trials of MCL-1 BH3 mimetics in patients with multiple myeloma, a disease with a MCL-1 dependent etiology." (PMID 30720718, 2019). "This strategy has already proven effective in pre-clinical studies of myeloma cells where the pan-CDK flavopiridol in combination with obatoclax led to decreased proliferation while preventing MCL-1 pro-survival signals and promoting the release of pro-apoptotic BIM." (PMID 30720718, 2019). "Increased lncRNA H19 expression induces bortezomib resistance in multiple myeloma by upregulating MCL-1 via sponging miR-29b-3p LncR-D63785 acts as a competitive endogenous RNA of miR-422a and promotes chemotherapy resistance by blocking miR-422-dependent suppression of MEF2D in gastric cancer." (PMID 31581131, 2019). "Moreover, MCL1 inhibitor S63845 promotes apoptosis in multiple myeloma, leukemia and lymphoma cells." (PMID 29484127, 2018). "The mechanism of resistance of neoplastic cells e.g., myeloma to bortezomib is not known with certainty, but accumulation of anti-apoptotic proteins e.g., MCL-1 due to interference with degradation has been implicated." (PMID 30445933, 2018). "In myeloma cells, miR-197 and miR-137 induce apoptosis by targeting Mcl-1." (PMID 29890998, 2018). "IL-6 upregulates Mcl-1 expression via activated STAT3 signaling in myeloma cells." (PMID 29340073, 2017). "MiR-197 induced apoptosis and suppressed multiple myeloma by targeting MCL-1." (PMID 28724426, 2017). "Indeed, clinical experience with SNS-032 in patients with chronic lymphocytic leukemia and multiple myeloma identified neutropenia as the dose-limiting side-effect, thought to be a consequence of decreased expression of Mcl-1 and XIAP." (PMID 28938529, 2017). "Our results suggest that combining inhibition of BCL-2 with drugs that reduce the expression or activity of MCL-1 may prove valuable for targeting auto-reactive or malignant PC in autoimmune disease or multiple myeloma, respectively." (PMID 27560714, 2016). "However, its most robust anti-myeloma properties seem to lie in its ability to promote apoptosis via the degradation of Mcl-1." (PMID 27363832, 2016). "Finally, treatment of the multiple myeloma KMS11 cell model (dependent on Mcl-1 for survival) with dexamethasone induced Bim and Bim-dependent lethality." (PMID 26231047, 2015). "As such, MCL1 was identified as the pivotal YM155 target in myeloma cells." (PMID 25974963, 2015). "Mcl-1 is an antiapoptotic member of the Bcl-2 family that is essential for myeloma cell survival." (PMID 26009993, 2015). "PDTC also increased levels of cleaved Mcl-1 and caspase-3 in U266 human myeloma cells, correlating with our murine data and validating the development of specific β-TrCP inhibitors as an alternative therapy to nonspecific proteasome inhibitors for myeloma patients." (PMID 26009993, 2015). "Indeed the balance Mcl-1/Bim was shown to be determinant in myeloma cell response to ATO and in the resistance of acute and chronic leukemic cells to fludarabine." (PMID 24956101, 2014).
multiple myeloma (continued). "Both pathways converged to down regulate anti-apoptotic Mcl-1 in myeloma cells." (PMID 25296978, 2014). "Nonetheless, when expressed inside cells the anchored PUMA and Bim BH3 α-helices powerfully induce cell death in the absence of efficient targeting to the mitochondrial membrane, whereas the Noxa helix requires a membrane insertion domain in order to kill Mcl-1-dependent myeloma cells." (PMID 24481451, 2014). "Moreover, bortezomib has been reported to induce apoptosis in myeloma cells by dissociation of Bim/Mcl-1 complexes, most likely through Noxa induction." (PMID 24594907, 2014). "Thus, targeting IL-6 triggered MCL-1 modulating molecules offers potential therapeutic approach to treat multiple myeloma." (PMID 25422792, 2014). "The elevated expression of MCL1 is a poor prognostic marker for Multiple Myeloma." (PMID 22558078, 2012). "However, expression of Mcl-1, which has been shown to be an important regulator of myeloma cell survival, was found to be decreased in NCI-H929 cells treated with 1 μM PBOX-15, with expression completely abolished after 48 h." (PMID 21179037, 2011). "In multiple myeloma Mcl-1 plays an important role in the survival of malignant cells." (PMID 21304176, 2010). "In addition, Mcl-1 expression correlates with disease grade and survival in human malignancies, e.g. in patients with multiple myeloma or B-cell non-Hodgkin's lymphoma." (PMID 17014711, 2006). "Numerous tumor types have been shown to utilize increased MCL1 expression to promote survival, including multiple myeloma, small cell lung cancer, and others, suggesting MCL1 could also confer a survival advantage to metastatic osteosarcoma cells in the hostile lung environment." (PMID 37676378, 2024). "In the case of MCL-1 with L267V mutation detected in myeloma patients, the mutation does not interfere with binding of MCL-1 inhibitors such as S63845 and AZD-5991 to MCL-1, rather it prevents displacement of pro-apoptotic proteins by the drug, resulting in disruption of the process of apoptosis." (PMID 36609747, 2023). "Moreover, it was reported that HDACi could inhibit the expression of MCL1 and BCL-XL as well as increase the expression of BIM in a variety of tumor cells, which may be associated with the synergistical anti-myeloma effect of chidamide and venetoclax." (PMID 35799216, 2022). "The present study aimed to determine whether the combination of BCL2 inhibitor venetoclax and MCL1 inhibitor S63845 at low doses could be of benefit for myeloma cells beyond the single selective inhibition of BCL2 or MCL1, especially for myeloma cells not dependent on BCL2 or MCL1." (PMID 32371863, 2020). "However, these previous studies mostly evaluate the effect of the BH3-mimetic combination on myeloma cells either sensitive to venetoclax or MCL1 inhibitors and consequently used different concentration of inhibitors according to the initial sensitivity of myeloma cells to each inhibitor." (PMID 32371863, 2020). "Furthermore, Atiprimod inhibited signal transducer and activator of transcription (STAT) 3 activation, blocking the signalling pathway of interleukin-6, which contributes to myeloma cell proliferation and survival, and downregulated the antiapoptotic proteins Bcl-2, Bcl-XL, and Mcl-1." (PMID 15970928, 2005). "The combination of the proteasome inhibitor carfilzomib and Mcl1 AUTAC synergistically promoted cell death in both in vitro models, including wild-type and proteasome inhibitor-resistant multiple myeloma and lung cancer cells, and in mouse tumor xenografts." (PMID 42115609, 2026). "MCL1 inhibitors like AMG 176, AZD5991, and S64315 are in trials for multiple myeloma, AML, and solid tumors." (PMID 41155156, 2025). "Most myeloma cells, except RPMI 8226, overexpress Mcl-1, suggesting these cells are dependent on Mcl-1 for survival." (PMID 39411073, 2024). "DT2216 sensitive myeloma cells expressed the highest levels of BCLXL and moderate levels of either BCL2, MCL1 or both." (PMID 37534243, 2023).
multiple myeloma (continued). "Among them, the widely studied MCL-1 inhibitor is BH3-mimic, which has good effects on blood system tumors and multiple myeloma and has made great progress in combination with established therapies." (PMID 37538176, 2023). "Herein, we describe the generation and characterization of the highly potent and selective MCL-1 inhibitor ABBV-467 and present findings from a first-in-human trial that included patients with relapsed/refractory multiple myeloma (NCT04178902)." (PMID 37880389, 2023). "In terms of cell viability, it was shown that among a panel of cancer cell lines derived from hematologic malignancies and solid tumors, the MCL-1 inhibitor appeared to be the most potent in AML and multiple myeloma, showing IC50 values of <1 μM." (PMID 37108344, 2023). "Specifically, BCL2L1, MCL1, and BCL2 were upregulated in AL‐amyloidosis compared with MM and controls." (PMID 36694297, 2023). "The expression of miR‐9‐5p, miR‐181a‐5p, BCL2, MCL1, and BCL2L1 in AL amyloidosis and MM patients was analyzed by t(11:14) status (which was determined by fluorescence in situ hybridization [FISH])." (PMID 36694297, 2023). "Since miRNAs regulate gene expression we used the bioinformatics tools IPA, miRTarBase, and TargetsScan, to explore a connection between the downregulated miRNAs in AL amyloidosis and the BCL2, BCL2L1, and MCL1 genes." (PMID 36694297, 2023). "For example, in myeloma cells, it activates the MAPK, PI3K⁄AKT, and NF-κB pathways, which leads to an up-regulation of Mcl-1 and Bcl-2 anti-apoptotic proteins." (PMID 35144648, 2022). "Clonal plasma cells in multiple myeloma have been found to be sensitive to inhibition of BCL-2 and MCL-1 at initial diagnosis, with increased MCL-1 dependence in relapsed disease, yet the heterogeneity in these dependencies has hampered treatment progress." (PMID 36184661, 2022). "Myeloma cells exhibit reliance on GLUT4 for basal glucose consumption, maintenance of apoptotic effector Mcl-1 expression, growth, and survival, while GLUT8 and GLUT11 are required for proliferation and viability in myeloma." (PMID 35912231, 2022). "This study found it to decrease MCL-1, BCL-XL, NOXA, and p21Cip1 expression in myeloma cells, leading to concurrent decreases in cyclin E and CCND2." (PMID 36364232, 2022). "Notably, this MCL-1 dependency is indirectly targeted by the proteasome inhibitor bortezomib, currently the standard of care for this disease and the related plasma cell disorder multiple myeloma, due to upregulation of pro-apoptotic Noxa and its inhibitory binding to MCL-1." (PMID 36184661, 2022). "BAFF and APRIL stimulate multiple myeloma cells through anti-apoptotic molecules such as BCL2, MCL1." (PMID 35144648, 2022). "Myeloid cell leukemia 1 (Mcl-1), a signal transducer and activator of transcription 3 (STAT3)-regulated molecule, is necessary for myeloma cell survival." (PMID 35637953, 2022). "Conversely, exposure to S63845 disrupted BIM/MCL-1 with compensational increased BIM/BCL-2 binding, in accordance with a recent report analyzing multiple myeloma cells." (PMID 35031695, 2022). "Immunoblot analysis revealed that the expression of BCL-XL and MCL-1 was reduced, suggesting the CUDC-907-induced death of myeloma cells in vitro." (PMID 33663586, 2021). "Mechanically, MM cells survival induced by MDSCs is dependent on AMPK activation, MCL-1 and BCL-2 expression in myeloma cells." (PMID 34095111, 2021). "For instance, dexamethasone renders myeloma cells more BCL-2 dependent while bortezomib and carfilzomib stimulate expression of the MCL-1 inhibitor NOXA, therefore reducing MCL-1 mediated venetoclax resistance." (PMID 34073976, 2021). "USP9X expression correlated with MCL-1 overexpression and/or poor outcome in follicular lymphoma, diffuse large B-cell lymphoma (DLBCL) and multiple myeloma (MM)." (PMID 33308268, 2020).
multiple myeloma (continued). "The analysis of the whole transcriptome data revealed different expression levels of several genes, such as JAK1, JAK2, JAK3, RAF, IL6R, NCAM (CD56), WHSC1, MCL1, BCL2, and IGF1, which showed myeloma pathogenesis." (PMID 30079703, 2019). "One such gene on chromosome 1q is MCL1, a BCL2-family anti-apoptotic protein that is induced during plasma cell differentiation and essential for plasma cell and myeloma cell survival." (PMID 31231360, 2019). "Some studies have indicated that bone marrow stromal cell-derived cytokine Interleukin-6 (IL-6) can upregulate MCL-1 and BCL-XL expression in myeloma cells, thus providing a possible mechanism of resistance to venetoclax." (PMID 30406027, 2018). "There is also optimism that BH3 mimetics such as AMG176, which can inhibit MCL-1 directly [see for review], will prove safe enough in ongoing AML and multiple myeloma studies (NCT02675452) to combine with venetoclax." (PMID 30406027, 2018). "In fact, studies in multiple myeloma cells indicate that HHT potentiates bortezomib activity through multiple mechanisms, including MCL-1 down-regulation and interference with stromal cell factors, among others." (PMID 30445933, 2018). "For instance, increased expression of the deubiquitinase USP9X, which is responsible for removing polyubiquitin chains that target MCL-1 protein for degradation, correlates with increased MCL-1 protein in FL, DLBCL, and multiple myeloma." (PMID 30671383, 2018). "In the same study, increased USP9X in multiple myeloma patients correlates with poor survival and the authors conclude that USP9X stabilizes MCL1, one member of pro-survival BCL2 family, and promotes tumor cell survival." (PMID 24152793, 2013). "This was achieved by analysis of the expression of MCL1, an antiapoptotic BCL2 family member, that is constitutively expressed in multiple myeloma cells." (PMID 22558078, 2012). "In multiple myeloma, all samples were effectively killed by co-targeting BCL2, BCLxL and MCL1." (PMID 40204951, 2025). "MCL1, an anti-apoptotic protein within the BCL-2 family, is frequently overexpressed in various cancers, including colon, esophageal, and ovarian cancers, as well as multiple myeloma, leukemia, and lymphoma." (PMID 39931465, 2025). "Certain hematological malignancies, such as AML and multiple myeloma, rely on MCL-1 for survival and may adopt the MCL-1 pathway to evade apoptosis in R/R contexts." (PMID 40973765, 2025). "Some myeloma cells resist immune-mediated cytotoxicity through intrinsic mechanisms involving the upregulation of anti-apoptotic proteins such as B cell lymphoma 2 (BCL-2), myeloid cell leukemia 1 (MCL-1), and B cell lymphoma-extra-large (BCL-XL)." (PMID 41470115, 2025). "Mcl-1 is classified as an antiapoptotic protein that is overexpressed in many types of IL-6-treated cancer cells, including prostate cancer, myeloma, gastric cancer, and cholangiocarcinoma cells, but not in control cells." (PMID 39272918, 2024). "Multiple myeloma is a very heterogeneous pathology, which is also manifested by its diverse addiction to the three main anti-apoptotic molecules such as BCL2, BCLXL and MCL1 for survival." (PMID 37534243, 2023). "A targeted proteomic approach using a mass cytometry panel of myeloma response markers after a 24-h exposure to ProRS inhibitors supports and extends the observed changes in the protein abundance of MYC, MCL-1 and SDC1." (PMID 36631435, 2023). "MCL-1–specific BH3 mimetics, which have entered clinical trials to treat MCL-1–dependent blood cancers like multiple myeloma, may also benefit from combination agents to broaden their therapeutic utility." (PMID 37956312, 2023). "Among them, the widely studied MCL-1 inhibitors are BH3-mimics, including AZD5991, S63845, MIM1, etc., which have good effects on hematological tumors and multiple myeloma and have made great progress in combination with established therapies." (PMID 37538176, 2023).
multiple myeloma (continued). "Additional MCL-1 specific inhibitors, including AMG 176 and AZD5991, were described in 2018 and shown to be efficacious at reducing tumor burden in murine models and are in clinical trials for lymphoma, multiple myeloma (MM), and acute myeloid leukemia (AML)." (PMID 37864894, 2023). "ChIP-seq assays showed that acetylation of H3K27 at cell cycle/mitochondrial gene promoters and super-enhancers of genes relevant for multiple myeloma biology (c-MYC, BCL-XL, CCND2, IRF4, MCL1, PIM1, PRDM1, and XBP1) was mildly increased in HDAC3 knockdown cells compared with nonsilencing cells." (PMID 36846090, 2022). "Myeloma cell lines and primary cells exhibit variable BCL2 family member expression and dependency, and in vitro venetoclax sensitivity in myeloma cells correlates to the relative expression of alternative pro-survival proteins, particularly MCL1." (PMID 35659041, 2022). "MDSCs inducing AMPK activation and MCL-1 and BCL-2 expression in myeloma cells." (PMID 34095111, 2021). "In human multiple myeloma (MM), diffuse large B cell lymphoma (DLBCL) and mantle cell lymphoma (MCL) cell lines, MCL-1 expression was also inhibited by OTS167, although by an unknown mechanism." (PMID 33658483, 2021). "In our study, myeloma cells poorly responding to both BCL2 and MCL1 inhibitors represented around 50% of patient samples, which could be found either at diagnosis or relapse." (PMID 32371863, 2020). "Indeed, flavopiridol blocks the growth of both multiple myeloma and chronic lymphocytic leukemia (CLL) cells, in which downregulation of Mcl-1, a Bcl-2 family member, was found to be flavopiridol’s primary mechanism of action." (PMID 32397434, 2020). "One anti-apoptotic protein that has been identified to be down-regulated in roscovitine-treated multiple myeloma (MM) cells is Mcl-1, whereby rapid down-regulation of Mcl-1 transcription and translation is independent of caspase cleavage." (PMID 31698798, 2019). "The small molecule S63845 (Servier Laboratories, Suresnes, France and Novartis, Basel, Switzerland) has been shown to bind with high affinity to the BH3-binding groove of MCL-1, resulting in apoptosis of MCL-1–dependent multiple myeloma, leukemia, and lymphoma cells." (PMID 30815228, 2019). "Indeed, a recent report investigated the role of MCL-1 in 20 NSCLC cell lines using a potent MCL-1 inhibitor and showed that only 5% of NSCLC cell lines, in contrast with 68% of multiple myeloma cell lines, are highly sensitive to MCL-1 inhibition." (PMID 30250075, 2018). "Furthermore, the combination treatment moderately enhanced the cytotoxicity and augmented apoptosis in myeloma cells via suppression of the AKT/mTOR pathway and the downregulation of Bcl-2 and Mcl-1 proteins." (PMID 28492559, 2017). "Conversely, growth inhibition and apoptotic cell death by YM155 was rescued by ectopic expression of Mcl-1 but not survivin, identifying Mcl-1 as the pivotal downstream target of YM155 in multiple myeloma." (PMID 25296978, 2014). "Notably, IL-6 upregulates Mcl-1 expression through the JAK/STAT3 signaling pathway, which not only induces the proliferation and survival of multiple myeloma cells but also increases mitochondrial bioenergy production and confers protection against mitochondrial dysfunction in cortical neurons." (PMID 39272918, 2024). "The BCL2/MCL1 ratio was not affected by t(11:14) in either AL amyloidosis or MM." (PMID 36694297, 2023). "Three studies have identified miR-137, which targets the anti-apoptotic gene MCL1, AURKA (a gene coding for a protein involved in mitosis and cell proliferation), and AKT, as a tumor suppressing miRNA, and its overexpression in MM cells sensitizes them to anti-myeloma drugs." (PMID 31698726, 2019). "MCL1 encodes two proteins belonging to the BCL2 family with either pro- or antiapoptotic functions; its overexpression has been detected in blood sample from a myeloma patient but not in his twin." (PMID 20459741, 2010).